CXCL12 (C-X-C motif chemokine ligand 12)
Diseases named in the same sentence as CXCL12 in open-access papers (continued):
Sharing a sentence is not in itself a finding about the gene and the disease.
melanoma (continued). "This is in line with the results of a previous study showing overexpression of CXCL12 in B16 melanoma–repelling antigen-specific T cells, suggesting complex and fine-tuned control of Teff infiltration by CXCL12/CXCR4 signaling." (PMID 35552271, 2022). "For example, in melanoma cells circ-0020710 binds more competitively to miR-370-3p than chemokine (C-X-C motif) ligand 12 (CXCL12) as miRNA sponge." (PMID 36384676, 2022). "And circ_0020710 promotes melanoma progression and immune evasion through the miR‐370‐3p/CXCL12 axis, indicating the importance of circRNAs in melanoma." (PMID 35274492, 2022). "In vitro and murine model experiments have demonstrated that CXCL12 is chemotactic for CD133+ melanoma cells." (PMID 36923305, 2022). "For example, miR-370-3p inhibits tumor growth and immune evasion by targeting CXCL12 axis in melanoma." (PMID 35779530, 2022). "Cycling hypoxia, akin to chronic hypoxia, reduces the expression of CXCL12 in WM793B melanoma cells." (PMID 33467722, 2021). "The major changes appear in the induction of mRNAs for chemokines CXCL12 and CCL21b, confirming the role of hypoxia in the metastatic process of melanoma cells." (PMID 33624446, 2021). "For example, circ_0020710 expedited the development and immune evasion of melanoma by sponging miR-370-3p to indirectly regulate CXCL12 expression." (PMID 34056112, 2021). "CXCL12 is a highly effective chemoattractant that is expressed in various cell types, including melanoma." (PMID 33925968, 2021). "Mechanistically, elevated circ_0020710 level upregulated CXCL12 expression to promote melanoma progression and induce immune evasion by sponging miR-370-3p." (PMID 32381016, 2020). "Through IHC analysis, we presented that CXCL12 level was significantly upregulated in melanoma tissues compared with paired normal tissues and benign nevi tissues." (PMID 32381016, 2020). "Activation of chemokine receptor CXCR4/CXCL12 signaling is also involved in TAMs recruitment of melanoma." (PMID 33224886, 2020). "All these findings above indicate that circ_0020710 serves as a ceRNA to contribute to melanoma progression through the miR370-3p/CXCL12 axis." (PMID 32381016, 2020). "In a mouse model of melanoma, tumors expressing high levels of CXCL12 inhibit cytotoxic T cells recruitment." (PMID 33096815, 2020). "Elevated circ_0020710 drives tumor progression via the miR-370-3p/CXCL12 axis, and circ_0020710 is a potential target for melanoma treatment." (PMID 32381016, 2020). "Transfection of CXCL12 into B16 melanoma cells induced DC accumulation within the tumor and reduced tumor growth in a CD8+ T cell-dependent manner." (PMID 30899263, 2019). "The CXCL12-loaded gel (CLG) attracted circulating CXCR4 positive melanoma cells diverting them from secondary sites." (PMID 31332163, 2019). "Targeting the interaction between the CXCR4 receptor and CXCL12 has been evaluated as a strategy for inhibiting CXCR4-CXCL12 axis-mediated melanoma metastasis." (PMID 31019223, 2019). "Thirdly, the use of specific CXCR4 inhibitors, T22 or a dimeric form of CXCL12, reduced lung metastases formation and inhibited the growth of primary melanoma tumors." (PMID 30420855, 2018). "We did, however, find directed migration of C8161 melanoma cells towards CXCL12-soaked beads in culture and a high percentage of cells surrounding the bead, confirming the invasive ability of these cells (data not shown)." (PMID 29175861, 2018). "For instance, K5-NS,OS was shown to inhibit the SDF-1/CXCL12 chemokine-mediated B16 melanoma cell proliferation and adhesion to endothelial cells and activated platelets, likely by interfering with the CXCL12–CXCR4 interaction." (PMID 30413079, 2018). "Administration of A2BR agonist Bay60-6583 enhances the expression of CXCL12 and FGF2 in melanoma-associated fibroblasts in an A2BR-dependent manner." (PMID 27590504, 2016).
melanoma (continued). "Melanoma-associated fibroblasts grown on polylysine-coated plates and treated with 10 nM Bay60-6583 for 24 hours showed increased expression of both FGF2 and CXCL12 compared to vehicle-treated cells (Ctr)." (PMID 27590504, 2016). "AMD3100 was administered to melanoma-bearing mice peritumorally to directly evaluate the possible involvement of the CXCL12/CXCR4 pathway in A2BR-mediated effects within tumor environment, minimizing possible systemic effects of this molecule." (PMID 27590504, 2016). "In a study on a melanoma mouse model paclitaxel treatment resulted in release of CXCL12 from platelets into the serum." (PMID 27835905, 2016). "The regulation of cytoskeletal reorganization and migration by RhoA in melanoma cells in response to the chemokine CXCL12 (SDF-1), has previously been described." (PMID 24069584, 2013). "Wnt5a was able to polarise the cellular cytoskeleton of melanoma cells through a process dependent on dishevelled, RhoB and Rab4 to promote cellular migration towards the source of the CXCL12 chemokine." (PMID 22655072, 2012). "Similar to the mouse melanoma model data, the S1 population (PDGFRAhi PDPNhi CD34hi) was characterized by the expression of genes involved in the regulation of immune cell recruitment (cytokines: CXCL12; complement factors: CFD, C3, C1S, CFH)." (PMID 36929873, 2023). "CXCL12 gene expression signature predicts response to CTLA-4 checkpoint blockade in melanoma." (PMID 35552271, 2022). "TPM1 and CXCL12 were alternatively spliced in the melanoma vs. nevus comparison." (PMID 34281234, 2021). "The involvement of CXCL12 in vascular metastasis of CSCs has also been described in melanoma." (PMID 33530455, 2021). "We show that primary human T cells adhere to endothelial vessel walls upon perfusion of microvessels and can be stimulated to undergo transendothelial migration (TEM) by TNFα-mediated vascular inflammation and the presence of CXCL12 gradients or ECM-embedded melanoma cells." (PMID 34361000, 2021). "Blocking CXCL12/CXCR4 using AMD3100 (a CXCR4 inhibitor) could improve the efficacy of anti-PD-1 in melanoma." (PMID 34911533, 2021). "Furthermore, circulating melanoma cells have been described to interact with perivascular MSCs through CXCR4/CXCL12 signaling and melanoma cell adhesion molecule (MCAM, CD146) in vivo, an interaction shown to be required for BM invasion." (PMID 33287630, 2021). "In addition, melanoma cells were shown to recruit pDCs into the tumor microenvironment via stromal-derived factor-1 (SDF-1, also named CXCL12)." (PMID 34737750, 2021). "The migration of T cells could be induced by adding the chemotactic trigger CXCL12 or a co-culture with the melanoma cell line A375 into the bottom perfusion lane." (PMID 34361000, 2021). "Additionally, ADM3100, a specific antagonist of the CXCR4/CXCL12 pathway, decreases the accumulation of TAMs and prevents B16 melanoma progression in mice." (PMID 33224886, 2020). "Moreover, CXCL12 is highly expressed in liver and specifically attracts melanoma and CXCR4 (+) cells, thereby increasing cancer liver metastasis." (PMID 33363463, 2020). "CXCL12 downregulation could reverse the malignant behavior of melanoma cells conferred by circ_0020710 over expression." (PMID 32381016, 2020). "Our results not only elucidate the potential mechanism by which circRNAs regulate the malignant progression and immune escape of melanoma, but also suggest that the circ_0020710/ CXCL12 axis could be a potential therapeutic target for melanoma patients." (PMID 32381016, 2020). "The potential role of CXCL12 was further explored in melanoma." (PMID 32381016, 2020). "On the one hand, elevated CXCL12 levels promoted melanoma progression through autocrine and paracrine pathways; on the other hand, elevated CXCL12 levels promoted immune suppressor cells recruitment to induce an immunosuppressive microenvironment, resulting in reduced CTL infiltration." (PMID 32381016, 2020).
melanoma (continued). "Notably, the bone tropism can also be attained by melanoma-derived exosomes, which are able to induce the CXCL12/CXCR4 axis." (PMID 33238004, 2020). "We then evaluated the roles of CXLC12 in melanoma by CXCL12 knockdown or overexpression." (PMID 32381016, 2020). "CXCL12 regulates invasion in melanoma and colorectal cancer and myeloma." (PMID 32260318, 2020). "We also selected CXCR4 (C-X-C motif chemokine receptor 4), since this gene was shown to be a direct target of miR-126-3p in colon and thyroid cancer cells and the CXCR4/CXCL12 (C-X-C motif chemokine ligand 12) axis is known to promote melanoma cell proliferation and invasiveness." (PMID 31227006, 2019). "Interestingly, melanoma growth in mice receiving Bay60-6583 was attenuated by inhibition of the CXCL12/CXCR4 pathway with AMD3100." (PMID 27590504, 2016). "The C-C chemokine receptor type 7 (CCR7) promotes melanoma cell metastasis to the C-C motif ligand 21 (CCL21)-rich lymph nodes while the C-X-C chemokine receptor type 4 (CXCR4)/C-X-C motif chemokine ligand 12 (CXCL12) axis facilitates pulmonary metastasis." (PMID 27598148, 2016). "As a GDP/GTP exchange factor, Vav1 is also involved in CXCL12-promoted invasion of melanoma cells." (PMID 24905577, 2014). "Indeed, high levels of CXCL12 have been shown to be fugetactic to lymphocytes and a B16 melanoma engineered to produce CXCL12 at high levels was found to be chemo-repellent to antigen-specific T cells." (PMID 22415233, 2012). "TAMs account for up to 30% of the melanoma tumor content and are polarized to an M2-like, immunosuppressive phenotype by melanoma cell-derived factors including but not limited to the B-cell lymphoma 2 protein, acidosis, colony-stimulating factor 1, CXCL12 and CCL2." (PMID 40838054, 2023). "Hence, inhibition of the CXCR4/CXCL12 pathway may represent a viable therapeutic pathway in melanoma." (PMID 36923305, 2022). "Thus, CCR10 and CXCL12/CXCR4 may regulate homing of CD4+ Tregs to B16 melanoma tumors while invasion of NBL tumors by CD4+ Tregs is likely governed by CCL28/CCR10 and CXCL12." (PMID 34721405, 2021). "Therefore, we speculated that circ_0020710 promoted the malignant progression of melanoma cells mainly through protecting CXCL12 from downregulation by miR-370-3p." (PMID 32381016, 2020). "In addition to tumor cells, CXCR4 is expressed by several other cell types, including macrophages and endothelial cells, and the CXCL12—CXCR4 pathway is associated with tumor progression, metastasis, and angiogenesis, also providing an attractive target for melanoma therapy." (PMID 26918341, 2016). "Thus, we sought to examine the expression of CXCL12 in melanoma sections using a specific antibody." (PMID 27590504, 2016). "Expression of the CXCL12/CXCR4 axis is increased in numerous cancer types, and it may serve as a diagnostic or prognostic biomarker in cancer patients, including those with melanoma." (PMID 27590504, 2016). "Melanoma-derived fibroblasts secrete factors such as C–C motif chemokine ligand 5 (CCL5), CCL2, and C-X-C motif chemokine ligand 12 (CXCL12), which induce immune checkpoint (ICP) ligand expression in melanoma cells, thereby compromising CD8+ T cell function." (PMID 40399946, 2025). "CXCL12, primarily secreted by stromal cells within the tumor microenvironment, binds to CXCR4 on the surface of melanoma cells, activating downstream signaling pathways that enhance tumor cell migration, invasion, and metastasis." (PMID 41346595, 2025). "The C-X-C motif chemokine ligand 12 (CXCL12) and its receptor CXCR4 play a crucial role in the metastasis of melanoma." (PMID 41346595, 2025). "CXCL12 is ubiquitously expressed in many tissues, and a distribution of CXCL12 similar to that of CXCR4 has been observed in melanoma cells." (PMID 38474372, 2024).
melanoma (continued). "Other chemokine ligands important during the metastatic process include the CXCR3 ligand CXCL10 (in melanoma and colorectal cancer), the CXCR4 ligand CXCL12 (in multiple types of cancer) and CCL1 (in melanoma)." (PMID 37744339, 2023). "The major chemokine/chemokine receptor interactions occurring in melanoma development and progression include the CXCR4/CXCR7/CXCL12, CXCR3/CXCL9,10,11, CXCR1,2/CXCL8, CCR2/CCL2, CCR4/CCL17,22, CCR5/CCL5, CCR7/CCL21 and CCR10/CCL27 axes." (PMID 37170733, 2023). "High concentrations of CXCL12, the ligand of CXCR4, are produced in the lungs and injected CXCR4-expressing B16 melanoma cells are able to efficiently colonize the lung." (PMID 35158973, 2022). "In WM793B melanoma cells and GOT1 cells (ileal carcinoids), chronic hypoxia reduces CXCL12 expression." (PMID 33467722, 2021). "Although multiple lines of evidence suggest that increased CXCL12 secretion by CAFs is pro-tumorogenic, further research is needed to explore to exact role of MAF-derived CXCL12 in the biology of melanoma." (PMID 32328671, 2021). "CXCL9, CXCL10, and CXCL12 are important chemotactic factors in the TME, which are able to recruit T cells and increase inflammation in tumors such as melanoma and lung adenocarcinoma." (PMID 34497764, 2021). "In this study, we observed a significant correlation (p≤ 0.05) between the DTH-PPD responses in BCG treated melanoma patients and the four gene SNPs from our panel: IL1β, NRAMP1/SLC11A1, and CXCL12." (PMID 33396862, 2020). "Agents targeting FAP-α, CXCR4/CXCL12, TGF-β, and other signaling in tumor stroma have been under preclinical study or clinical trials for various cancers including melanoma." (PMID 32373541, 2020). "Preisner and colleagues used qRT-PCR to analyze the expression of 229 tumor-promoting genes in melanoma cells cocultured with ADSCs and found similar cytokines and growth factors, such as IL6, CXCL12, VEGF, and HGF69." (PMID 32848147, 2020). "In melanoma, CXCR4 inhibition with AMD11070 abrogated tumor cell migration in response to CXCL12 stimulation." (PMID 30420855, 2018). "In summary, this study shows that A2BR activation in tumor-associated fibroblasts triggers the expression of microenvironmental tumor-promoting factors in a murine model of melanoma, including FGF2 and CXCL12." (PMID 27590504, 2016). "Knockdown of Vav1 by RNAi in melanoma cells led to impaired activation of the Jak/Vav1/RhoGTPases (Rac1 and RhoA) pathway, blocking up-regulation of MT1-MMP by CXCL12, a mechanism that contributes to melanoma cell invasion." (PMID 25313137, 2014). "Most chemokines were expressed intracellularly in all melanoma cell lines (CXCL9, CXCL11, CXCL12, CCL19, CCL21 and CCL27)." (PMID 24559071, 2014). "The four peptides efficiently inhibited CXCL12-dependent migration at concentrations as low as 10 nM and delayed CXCL12-mediated wound healing in PES43 human melanoma cells." (PMID 24058588, 2013). "The limitation is that these previous studies focused on the CXCL12/CXCR4 function on metastatic melanoma cells but not in the adjacent cells that are part of the TME." (PMID 39496484, 2024). "It is important to note that the CXCL12/CXCR4 axis activates the AKT and ERK cell signalling pathways, and we have recently demonstrated that a reciprocal activation between the RUNX2 and AKT/ERK pathways occurs in melanoma." (PMID 38474372, 2024). "In addition, a commercially available dermal filler, hyaluronic acid (HA)-based gel, loaded with CXCL12 was able to recruit and trap CXCR4-expressing B16 melanoma cells injected into mice, consequently leading to a reduction in lung metastases." (PMID 35158973, 2022). "Interestingly, a subset of SASP components, including cytokines CCL2, CCL3, CXCL12, cathepsin CTSD, or the protease inhibitor SERPINE1, are secreted in a RAB27A‐dependent manner in senescent melanoma cells." (PMID 36087066, 2022). "Melanoma cells also express CXCR‐4, a chemokine receptor, with CXCL12 as a corresponding ligand." (PMID 36398426, 2022).
melanoma (continued). "After the transfection efficiency was verified by western blot, CCK-8 and colony formation assays showed that the cell viability was inhibited after CXCL12 knockdown, and wound healing, transwell invasion assays revealed that CXLC12 knockdown decreased cell migration, invasion of melanoma cells." (PMID 32381016, 2020). "Oxidative stress induced by hypoxia in the melanoma as well as factors secreted by melanoma cells stimulate MAFs to secrete cytokines and growth factors such as VEGF, stromal derivative factor-1 (SDF-1 or CXCL12) and IL-6 thus promoting invasion into the melanoma." (PMID 32984031, 2020). "To test whether NGF altered the proliferation of C8161 metastatic melanoma cells, we measured changes in proliferation in co-culture experiments with NGF, BDNF, CXCL12 and NT3 by BrdU incorporation (30-min pulse)." (PMID 29175861, 2018). "Circulating pDCs from patients with melanoma have been found to express higher amounts of CCR6 and CXCR4, while their corresponding ligands CCL20 and CXCL12 are expressed on melanoma cells, suggesting that the CCR6/CCL20 and CXCR4/CXCL12 axes promote pDC migration from blood to melanoma foci." (PMID 29085361, 2017). "In vitro, melanoma cell lines are also able to adhere to endothelial cells in a process involving αvβ3 integrin, α4β1-integrin, endothelial VCAM-1, Lu-ECAM-1, as well as the chemokines, including CXCL12." (PMID 28253287, 2017). "Notably, CXCR7 alterations had no impact on the secretion of CXCL12 from melanoma cells." (PMID 30804329, 2019). "The B16.F10 melanoma cells used in our experimental model did not express CXCL12 or CXCR4, ruling out direct effects on melanoma cells." (PMID 27590504, 2016). "The role in melanoma of the recently discovered CXCR7, which binds to CXCL11 and CXCL12 is still not clear." (PMID 24559071, 2014).